SMAD3 (SMAD family member 3)
Diseases named in the same sentence as SMAD3 in open-access papers (continued):
Sharing a sentence is not in itself a finding about the gene and the disease.
glioma (continued). "Furthermore, we also found that over-expressed Smad3 induced secretion of miR-21 from glioma cells into extracellular environment." (PMID 27166186, 2016). "However, the relative involvement of Smad2 and Smad3 in the control of TGFβ2-induced cell proliferation in glioma cells remains to be elucidated." (PMID 25891822, 2015). "However, another study indicated miR193b as a cancer oncogene by targeting Smad3 in human glioma." (PMID 32596290, 2020). "However, the regulation mechanism of CEBPB on TGFB1/SMAD3 in glioma was seldom studied." (PMID 27716259, 2016). "Thus, this evidences suggests that HOXA13 knockdown may cause G0/G1 arrest by inhibiting SMAD2/SMAD3 pathway and this process could be regulated by HOTTIP in glioma." (PMID 26356815, 2015). "In summary, our findings indicate that the JICD1 transcriptional complex contributes to the invasive phenotype of glioma cells with DDX17 and linker-phosphorylated SMAD3." (PMID 38092725, 2023). "In the present study, we showed that diosmetin inhibits TGF-β signaling in glioma cells by suppressing the expression of TGF-β and elevating the levels of the active forms of Smad proteins (i.e., p-Smad2 and p-Smad3)." (PMID 31906574, 2020). "In human gliomas, miR-193b can reduce the expression of SMAD family member 3 (Smad3) to promote cell proliferation." (PMID 32722316, 2020). "It has been shown that the TGFβ level is elevated in higher grades of gliomas and its signaling pathway regulates tumor progression through phosphorylation of SMAD2 and SMAD3, which form a complex with SMAD4 to regulate target gene transcription." (PMID 29861845, 2018). "In a TCGA study with merged cohort of Low Grade Glioma (LGG) and GBM, PJA1, PJA2 Smad3 and altered in 9%, 4% and 14% of samples, respectively." (PMID 28966725, 2017). "Meanwhile, we found that the phosphorylated levels of TGFBR1, Smad2 and Smad3 and the nuclear levels of Smad2/Smad3 were markedly increased in the SMC4-overexpressing glioma cells but decreased in the SMC4-silenced cells." (PMID 28287612, 2017). "Further targeting TGF-β/Smad3 signaling using galunisertib, an inhibitor of the TGF-β type I receptor kinase, can attenuate the secretion of miR-21 from glioma cells." (PMID 27166186, 2016). "Above results suggested that Smad3 activity was essential for production and release of miR-21 induced by TGF-β1 in glioma cells." (PMID 27166186, 2016). "The western blot results also demonstrated reduced basal levels of Smad-1, Smad-3 and TGF-β proteins in miR-211 and IR-treated cells when compared to control glioma CSC." (PMID 23183822, 2012). "Our results also indicated that phosphorylation of the SMAD3 linker domain may be crucial for the formation of the JICD1 transcriptional complex and glioma cell invasion." (PMID 38092725, 2023). "Our results further suggest that CSF-based miR-21 might be secreted by glioma cells and TGF-β/Smad3 signaling pathway was responsible for regulating miR-21 secretion." (PMID 27166186, 2016). "Likewise,SMAD3 downregulation by CMA augmented proliferation and invasion of glioma cells,supporting the negative correlation between SMAD3 expression and tumor developmentreported in previous studies." (PMID 38829285, 2024). "Thus, the activity of Smad3 and HIF-1α could represent the main molecular targets for treatment of gliomas because these proteins may coordinate the basic aspects of cancer stem cell biology." (PMID 34707087, 2021). "Therefore, the present study investigated how downregulation in the expression levels of Smad2 and Smad3 affected glioma cell proliferation, and whether GBM cell proliferation was controlled differentially by Smad2 and Smad3." (PMID 25891822, 2015).
keloid (25 papers, 2013 to 2025). An irregularly shaped, elevated mark on the skin caused by deposits of excessive amounts of collagen during wound healing. "MicroRNA-152-5p inhibits keloid fibroblast proliferation and migration while promoting apoptosis by directly targeting Smad3." (PMID 41424791, 2025). "To date, studies on how transforming growth factor (TGF)-β1/Smad3 signaling pathways interact with keloid are the most detailed, in which TGF-β1 plays an important role in keloid formation." (PMID 36313222, 2022). "We previously showed that silencing of the TGF-β family member GDF-9 in keloid-derived fibroblasts downregulated p-Smad2 and p-Smad3." (PMID 33628711, 2021). "For example, down-regulation of miR-637 promoted proliferation and metastasis by targeting Smad3 in keloids." (PMID 33817252, 2020). "The expressions of PARP1 and Smad3 were significantly higher in keloid tissue." (PMID 31119062, 2019). "In addition, the keloid sections were incubated with antibodies against Phospho-Smad2/Smad3, Phospho-Erk1/2, CD31, CD34, collagen I, and collagen III at a dilution of 1:500." (PMID 27339758, 2016). "Indeed, immunohistochemical analysis in the keloid sections showed intense phosphorylated forms of Smad2/Smad3, which are central mediators of intracellular TGF-β signal transduction." (PMID 27339758, 2016). "Additionally, treating keloid derived fibroblasts with INF-γ significantly increased the expression of Smad3 and Smad7 in a time and dose dependent manner." (PMID 26236109, 2015). "Key hub proteins such as SMAD3, BMP4, and WNT5A are centrally positioned, suggesting their potential roles as critical regulators in keloid pathogenesis." (PMID 41278551, 2025). "Since an overabundance of collagen synthesis is a tell-tale sign of keloids, they evaluated types I and III procollagen expression after the downregulation of Smad3 by siRNA-3." (PMID 36483731, 2022). "A previous study reported features of EMT in keloid scar epidermis, including increased levels of TGF-β1 and phosphorylated Smad3 compared to normal epidermis, and decreased E-cadherin levels." (PMID 27574697, 2016). "More recent genetic research has identified several genes, such as SMAD3, EN2, and NDFIP1, that may play crucial roles in keloid pathogenesis." (PMID 39119435, 2024). "Furthermore, a lipocalin (ADP355) -based peptide is also capable of inhibiting TGF-β1-induced fibrosis in keloids and can potentially treat keloids through modulation of signaling pathways such as AMPK, SMAD3, and ERK." (PMID 38046417, 2023). "The findings of this study demonstrated that adMSC-Exos inhibited ECM deposition in keloids, which may have been mediated by inhibition of the TGF-β2/Smad3 and Notch-1 signaling pathways." (PMID 35333672, 2022). "hAMSC-CM prevented the proliferation and activation of keloid fibroblasts and hAESC-CM attenuated TGF-β1-induced human dermal fibroblast transformation to myofibroblasts via TGF-β1/Smad3 pathway, suggesting that hAESC-secreted cytokines might promise for keloid treatment as a topical agent." (PMID 33478081, 2021).
Insulin resistance (24 papers, 2013 to 2025). Increased resistance towards insulin, that is, diminished effectiveness of insulin in reducing blood glucose levels. "These Smad3-deficient db/db mice (Smad3KO-db/db) demonstrate β cell hyperplasia, persistent hyperinsulinemia, normal glycemia, recovered glucose tolerance, and eliminated insulin resistance." (PMID 35327565, 2022). "• Increase insulin resistance through TGFβ/Smad3 signaling via the repression of the insulin promoter and suppression of insulin level and secretion. • Inhibition of adipocyte differentiation. • Correlation with high levels of serum glucose." (PMID 35422689, 2022). "In particular, the activation of SMAD3 appears to play a critical role in TGFβ1-mediated insulin resistance." (PMID 36430743, 2022). "Here we also showed that deletion of Smad3 protected against glucose intolerance and insulin resistance in db/db mice." (PMID 33456576, 2021). "The excess FFA activates the TGF-β signaling pathway to induce insulin resistance through Smad-3-mediated downregulation of the Fndc5 gene." (PMID 33060792, 2020). "In adipose tissue, the TGFβ/Smad3 signaling has been demonstrated as a metabolic regulator that links the development of insulin resistance, lipid metabolism and inflammatory responses." (PMID 30709353, 2019). "The findings of our study may provide new determinants by which the increase in SMAD3 levels can contribute to the development of insulin resistance in skeletal muscle." (PMID 39825925, 2025). "We also examined whether the increase in SMAD3-PAI-1 could mediate insulin resistance through a different mechanism." (PMID 39825925, 2025). "In conclusion GDF-15 could have an adverse effect on sarcopenia and decrease skeletal muscle mass by activating FOXO1 and SMAD3, however, its protecting role against insulin resistance could reverse the process of sarcopenia." (PMID 38409184, 2024). "Experimental study shows that sEVs from bone marrow stem cells increase the gene expression of insulin signal pathway (insulin, Pdx1, Smad2, Smad3, and transforming growth factor β) in the type 1 diabetes condition and alleviate insulin resistance in the T2D rat model." (PMID 37593852, 2023). "In addition to preventing muscle hypertrophy, MSTN has also been shown to induce insulin resistance in a mechanism dependent on nuclear factor kappa-light-chain-enhancer of activated B cells (NF-κB) and SMAD family member 3 (SMAD3)." (PMID 35330038, 2022). "Myostatin was also found to signal via the nuclear factor kappa-light-chain-enhancer of activated B cells (NF-κB), which, together with SMAD3 activation, could affect glucose uptake inducing insulin resistance." (PMID 32796600, 2020). "Interestingly, the transcription factor Smad3 plays a key role in the inhibition of adipocyte differentiation and in the development of insulin resistance." (PMID 24040759, 2013). "This type of cytokine correlates with obesity induced insulin resistance and TGF-Β-β/Smad3 signaling pathway plays key roles in development of insulin resistance in genetically obese mice." (PMID 26755467, 2015). "It is plausible that the interactions of TGF β /Smad3 with PI3K/AKT singaling pathways led to impaired insulin signaling in the periphery, which may partly contribute to the insulin resistance in db/db mice." (PMID 33456576, 2021). "Given the proposed role of the SMAD3-PA-I pathway in insulin resistance, these data suggest that deciphering the mechanisms involved in regulation of nuclear GDF15 levels may evolve into a new strategy to prevent the development of insulin resistance and T2DM." (PMID 39825925, 2025). "Previous studies suggested that AMPK activators, including metformin, can improve insulin resistance, liver steatosis, and dyslipidemia through the inactivation of sterol regulatory element-binding protein (SREBP), hepatic stellate cell activation, and the TGF-β1/Smad3 pathway." (PMID 40649054, 2025).
Insulin resistance (continued). "In particular, Smad3 KO-db/db mice developed hyperinsulinemia through the lifetime but not insulin resistance, suggesting that Smad3 might also modulates peripheral glucose metabolism and insulin action in a unique manner." (PMID 33456576, 2021).
Peritoneal Fibrosis (23 papers, 2012 to 2025). Disorder characterized by a wide range of structural changes in PERITONEUM, resulting from fibrogenic or inflammatory processes. "In this research, we reported that SIRT1 knockout also upregulated the protein levels of TGF-β (p < 0.001) and pSMAD3 (p < 0.01) in PD mice, indicating that SIRT1 deficiency activated the TGF-β/SMAD3 pathway and enhanced peritoneal fibrosis." (PMID 33906673, 2021). "As the TGF-β/Smad3 signaling pathway has been reported to be implicated in the pathogenesis of peritoneal fibrosis, we examined the effect of Src inhibition on the activation of this pathway." (PMID 29137389, 2017). "Intraperitoneal administration of bone morphogenetic protein 7 inhibits peritoneal Smad3 expression and its phosphorylation, peritoneal fibrosis, inflammation, and angiogenesis in a chlorhexidine gluconate-treated model in uremic rats." (PMID 39201294, 2024). "At the same time, Canagliflozin significantly inhibited the HIF-1α/TGF-β/p-Smad3 signaling, prevented peritoneal fibrosis and peritoneal thickening, and improved peritoneal transportation and ultrafiltration." (PMID 37251320, 2023). "Five-week intraperitoneal injection of 4.25% peritoneal dialysate remarkably increased peritoneal HIF-1α/TGF-β/p-Smad3 signaling and promoted peritoneal fibrosis and peritoneal thickening." (PMID 37251320, 2023). "TGF-β1/Smad3 signaling pathway is proved to be critical in the pathology studies of peritoneal fibrosis, and recent research reports that exposure to TGF-β1 can induce the M2 polarization in macrophages." (PMID 35784347, 2022). "Considering the role of TGF-β/Smad3 signaling in macrophage polarization, we also detected the regulation of TA on TGF-β/Smad3 during peritoneal fibrosis in this study." (PMID 35784347, 2022). "We found that this SIRT1-modified hUCMSCs ameliorated experimental peritoneal fibrosis by inhibiting the TGF-β/Smad3 pathway." (PMID 33906673, 2021). "Inhibition of autophagy with 3-MA prevents peritoneal fibrosis by regulating TGF-β/Smad3, EGFR/ERK1/2, STAT3/NF-κB and β-Catenin axis both in vivo and in vitro systems." (PMID 34497522, 2021). "Our results indicated that suramin can attenuate progression of peritoneal fibrosis by a mechanism involving inhibition of the TGF-β1/Smad3 and EGFR signaling pathways as well as suppression of multiple proinflammatory cytokines." (PMID 31727005, 2019). "Smad3 signalling triggered TGF‐β1‐induced EMT and fibrosis that has been demonstrated that Smad3 knockout mice can be protected from peritoneal fibrosis (PF) with loss of collagen accumulation." (PMID 29077259, 2018). "PD-related peritoneal fibrosis is associated with a loss of miR-29b, and intraperitoneal delivering of plasmid expressing this miRNA in mice inhibited peritoneal fibrosis through an effect on TGF-β/Smad3 pathway." (PMID 26941801, 2016). "We analyzed Smad3 activity, which is involved in the onset of peritoneal fibrosis after exposure to TGF-β1." (PMID 22384029, 2012). "The Smad3 is a signal transducer, and the Smad3-deficient mice are resistant to the TGF-β1-induced peritoneal fibrosis." (PMID 22384127, 2012). "TGF-β/Smad3 signaling plays an important role during peritoneal fibrosis." (PMID 37251320, 2023). "Herein, we examined TGF-β/Smad3 protein levels to investigate whether they participated in CoCl2 hypoxia-induced peritoneal fibrosis and the therapeutic mechanisms of Canagliflozin." (PMID 37251320, 2023). "Our results support that the HDAC6 could enhance M2 polarization to promote peritoneal fibrosis via regulating the TGF-β/Smad3 signaling." (PMID 35784347, 2022). "All these results indicated that SIRT1-modified hUCMSCs ameliorate peritoneal fibrosis which might be through the inhibition of the TGF-β/Smad3 pathway." (PMID 32811535, 2020). "Therefore, TA could inhibit TGF-β1/Smad3 signaling pathway, and then prevent M2 macrophage polarization in peritoneal fibrosis." (PMID 35784347, 2022).
Peritoneal Fibrosis (continued). "In summary, we demonstrated that Canagliflozin prevents peritoneal fibrosis induced by high glucose and improves peritoneal function by alleviating peritoneal hypoxia and inhibiting HIF-1α and TGF-β/p-Smad3 signaling pathways." (PMID 37251320, 2023). "In situation of peritoneal fibrosis, TGF-β/SMAD3 signaling axis has been recognized to mediate EMT process." (PMID 33514826, 2021). "Mechanistically, SIRT1-modified hUCMSCs attenuated peritoneal fibrosis through reducing peritoneal inflammation and inhibiting the TGF-β/Smad3 pathway in peritoneal omentum tissues." (PMID 32811535, 2020). "To explore the mechanism by which Src activation contributes to peritoneal fibrosis, we examined the effect of Src inhibition on the expression of TGF-β receptor I and II as well as the phosphorylation (activation) of Smad3 in the peritoneum after CG injury." (PMID 29137389, 2017). "The role of Smad3 signaling in TGF-β1 induced EMT and fibrosis is demonstrated in vivo in Smad3 knockout mice, which are protected from peritoneal fibrosis, show reduced collagen accumulation, and display attenuated EMT." (PMID 26941801, 2016). "Intraperitoneal administration of gefitinib, an inhibitor of epidermal growth factor receptor, suppresses TGF-β1 expression, phosphorylation of Smad3, STAT3, and nuclear factor-κB (NF-κB), which leads to reduction in peritoneal fibrosis and a number of CD31-positive blood vessels in the model." (PMID 39201294, 2024). "In conclusion, we showed that Canagliflozin could improve peritoneal fibrosis and function by ameliorating peritoneal hypoxia and inhibiting the HIF-1α/TGF-β/p-Smad3 signaling pathway, providing theoretical support for the clinical use of SGLT2 inhibitors in patients on peritoneal dialysis." (PMID 37251320, 2023). "Thus, in addition to the TGF-β/Smad3 signaling pathway, Src may also regulate the EMT and peritoneal fibrosis through activation of the PI3K/Akt and STAT3 pathways." (PMID 29137389, 2017). "Importantly, Smad3−/− mice were not protected from SES-induced peritoneal fibrosis, suggesting that TGF-β signaling is not required for the observed fibrotic changes." (PMID 24412616, 2014).